SCD (stearoyl-CoA desaturase)
Diseases named in the same sentence as SCD in open-access papers (continued):
Sharing a sentence is not in itself a finding about the gene and the disease.
lung carcinoma (continued). "The present study also explored the clinical relevance of SCD expression in lung cancer patients." (PMID 36514170, 2022). "CSCs maintenance also seems to depend upon the size of the pool of monounsaturated fatty acids (MUFAs) generated by the activity of the stearoyl-CoA desaturase 1 (SCD1) because SCD1 inhibition was shown to selectively eliminate CSCs in lung cancer, both alone and in synergy with chemotherapy." (PMID 33202944, 2020). "Furthermore, SCD1 silencing reduces the survival of prostate cancer cell lines and cell proliferation and tumor in lung cancer and animal models reinforcing the idea that SCD can be a novel therapeutic target against some tumors." (PMID 31936134, 2020). "In this report, we show that inhibition of SCD activity in human lung cancer cells with the small molecule SCD inhibitor CVT-11127 reduced lipid synthesis and impaired proliferation by blocking the progression of cell cycle through the G1/S boundary and by triggering programmed cell death." (PMID 20613975, 2010). "Stearoyl-CoA desaturase (SCD), an enzyme that catalyzes the rate-limiting step in monounsaturated fatty acid synthesis, has recently been identified as a ferroptosis-related gene in various cancers, including bladder cancer, cervical cancer, ovarian cancer, and lung cancer." (PMID 36672408, 2023). "STK11/KEAP1 co-mutations lead to a notable increase in the expression of ferroptosis-protective genes, including SCD and AKR1C1/2/3, as well as resistance to drug-induced ferroptosis in lung cancer cells." (PMID 37728413, 2023). "The upregulation of SCD and SCD1 gene expression is a key factor for lung cancer-initiating cells and marked poor prognosis along with increased metastasis in in vitro and in vivo studies." (PMID 33916349, 2021). "FADS2 has been shown to play a key role in FA desaturation in different cancer cell lines and primary tumors that are resistant to SCD inhibitors, and simultaneous blocking of both SCD and FADS2 resulted in a significant tumor reduction in hepatocellular and lung carcinoma xenografts." (PMID 40723225, 2025). "Additionally, research indicates that CAFs in lung cancer, through HIF-1α, increase the expression of stearoyl-CoA desaturase 1 (SCD1), thereby increasing the number of lipid droplets in cells and promoting lung cancer growth." (PMID 39769177, 2024). "This contrasts with A549 lung cancer cells, which constitutively express higher levels of Zeb1, and in which SCD inhibition already has a pro-ferroptotic effect without TGFβ stimulation." (PMID 39009641, 2024). "Similarly, cryptotanshinone (CTS), a bioactive component of Salvia miltiorrhiza, was shown to sensitize gefitinib‐resistant EGFR‐mutant lung cancer cells by targeting catalase (CAT), heme oxygenase 1 (HMOX1) and stearoyl‐CoA desaturase (SCD)." (PMID 37697969, 2023). "NFE2L2 activity is further enhanced by serine/threonine kinase 11 (STK11) and KEAP1 co-mutation, which induces expression of ferroptosis-protective genes, such as stearoyl-CoA desaturase (SCD) and aldo-keto reductase 1 C family 1/2/3 (AKR1C1/2/3) in lung cancer cells." (PMID 34742351, 2021). "Both stable SCD1 gene knockdown and acute pharmacological inhibition of SCD induced AMPK activation and the subsequent phosphorylation of ACC in lung cancer cells, suggesting a second mechanism for the inhibition of fatty acid synthesis and lipogenesis observed in SCD1-deficient cells." (PMID 19710915, 2009). "Additionally, the SCD inhibitor CVT-11127 induces cell cycle arrest in H460 lung cancer cells without impairing the proliferation of normal human fibroblasts." (PMID 38610991, 2024). "Consequently, inhibition of SCD and FADS2 promotes ferroptotic cell death in lung cancer." (PMID 34742351, 2021).
diabetes (73 papers, 2005 to 2025). "The importance of SCD in beta cells is also documented by the loss of SCD1 in leptinob/ob mice, leading to an accelerated progression to overt diabetes." (PMID 19787047, 2009). "Increased SCD activity is indicated by the orange arrows between all SCD-linked SFAs and MUFAs (e.g. 16∶0 to 16∶1n7 and 18∶0 to 18∶1n9 nodes), while the diabetes-associated decrease in SPCS activity is reflected in the blue arrows linking 22∶6n3 with 22∶5n3 and 22∶4n6 with 22∶5n6." (PMID 23144998, 2012). "Diabetes was associated with increases in both measures of SCD activity." (PMID 23144998, 2012). "SCD is one of the genes that is involved in ameliorating the neuropathic phenotype induced by diabetes by restoring aberrant fatty acid biosynthesis and thereby preventing altered myelin lipid profile and ensuing myelin structural abnormalities." (PMID 34359773, 2021). "The regulation of BM-MSCs of patients with type 2 diabetes mellitus (T2DM) by SCD-1 is a necessary condition for osteogenesis mediated through the miR-203a/FOS and miR-1908/EXO1 regulatory pathways." (PMID 33319811, 2020). "In subcutaneous adipose tissue (SAT), higher stearoyl-CoA desaturase-1 (SCD1) expression has been related to improved insulin sensitivity in thiazolidinedione-treated type 2 diabetes mellitus patients." (PMID 30190473, 2018). "In fact plasma markers of peroxisome-dependent VLCPUFA chain-shortening in both omega-3 and omega-6 pathways were reduced in diabetes, which also inversely correlated with SCD activity." (PMID 23144998, 2012). "SCD-1 is the key enzyme involved in the endogenous synthesis of MUFAs, and its expression and activity are increased in several types of diseases including diabetes and cancer." (PMID 40167637, 2025). "Conversely, when overexpressed, SCD is involved in metabolic diseases such as diabetes and NAFLD, by regulating the canonical Wnt pathway through the activation of β-catenin and the consequent activation of hepatic stellate cells (HSCs), which support liver cell degeneration." (PMID 35334792, 2022). "Another SCD inhibitor showed beneficial therapeutic effects against diabetes and dyslipidemia." (PMID 34576047, 2021). "A genetic predisposition to lower the SCD expression, therefore, might contribute to the development of diabetes mellitus, however, to the extent that this may occur is not yet clear." (PMID 36292669, 2022). "Stearoyl-CoA desaturase 1 (SCD1), the main enzyme responsible for producing monounsaturated fatty acids(MUFA) from saturated fatty acids, is frequently deregulated in both diabetes and CRC." (PMID 29530061, 2018). "PAHX and SCD-1, another enzyme downregulated in NOD diabetic mice, play a sequential role in peroxisomal lipid processing, suggesting that disruptions in lipid homeostasis occur in diabetes and proteinuria." (PMID 16371158, 2005).
ovarian carcinoma (72 papers, 2012 to 2026). A malignant neoplasm originating from the surface ovarian epithelium. "Stearoyl-CoA Desaturase 1(SCD1) is an enzyme that catalyzes the synthesis of monounsaturated fatty acids in ovarian cancer cells and is highly expressed in ovary tumor cells." (PMID 39192972, 2024). "A recent study has demonstrated that inhibiting SCD can trigger both ferroptosis and apoptosis in ovarian cancer cells." (PMID 39107713, 2024). "Stearoyl-CoA desaturase 1 (SCD1), the enzyme that produces these fatty acids, is highly expressed in many cancers, including breast, prostate, renal, lung, and ovarian cancer, making SCD1 an attractive target for cancer therapy." (PMID 37712874, 2023). "The expression of various fatty acid metabolizing enzymes such as stearoyl-CoA desaturase 1 (SCD1) was altered in early-stage ovarian cancer tissue compared with that in normal ovarian tissue." (PMID 37712874, 2023). "The inhibition of SCD expression can induce cancer cell apoptosis: when SCD inhibitors were applied to treat the primary ovarian cancer stem cells, the stemness markers were down-regulated." (PMID 38003694, 2023). "In ovarian cancer, SCD expression or palmitoleic acid supplementation (a type of MUFA) can confer ferroptosis resistance to cancer cells." (PMID 37957645, 2023). "Blockade of SCD leads to reduced content of unsaturated fatty acids and suppression of NF-κB signaling, thereby restraining ovarian cancer stem cells." (PMID 35370706, 2022). "Concurrent with SCD-1 overexpression being related to cancer progression and growth, SCD-1 overexpression has also been shown to protect ovarian cancer cells from ferroptotic cell death." (PMID 34421820, 2021). "SCD is highly expressed in ovarian cancer tissues and cell lines and inhibits SCD-induced cell death." (PMID 35087751, 2021). "Stearoyl-CoA desaturase (Scd) family catalyze the desaturation of saturated acyl-CoA, and Scd1 was nearly reported to be a protective factor in ovarian cancer cells from ferroptotic cell death induced by RSL-348,49." (PMID 32934217, 2020). "Stearoyl-CoA desaturase 1 (SCD1) suppresses ovarian cancer cell ferroptosis, while the inhibition of pharmaceutical SCD1 promotes ferroptosis in vitro and in vivo, and the combined treatment of SCD1 inhibitors and ferroptosis inducers significantly inhibits ovarian tumor growth." (PMID 35805124, 2022). "A study confirmed that SCD was an enzyme that catalyzes the rate-limiting step in monounsaturated fatty acid synthesis in ovarian cancer cells; inhibition of SCD1 could induce both ferroptosis and apoptosis." (PMID 34422642, 2021). "Stearoyl CoA desaturase (SCD1), an enzyme that catalyze the rate-limiting step of monounsaturated fatty acid synthesis in fat, is highly expressed in ovarian cancer tissues, cell lines, and ovarian cancer stem cells." (PMID 33574983, 2021). "The role of lipids, and particularly of MUFAs, in sustaining survival is crucial not only for normal tissue but also for cancer cells, where, in several solid malignancies such as breast, lung, prostatic, colorectal and ovarian carcinoma, an important role for SCD-1 has been shown." (PMID 28452935, 2017). "Indeed it has already been shown in glioma cells that SCD inhibition results in distinct downstream effects and both apoptotic and ferroptotic cell death pathways are triggered in response to SCD inhibition in ovarian cancer." (PMID 39187579, 2024). "SCD inhibitors such as MF-1, A939572, and CAY438 inhibit the formation of MUFAs, enhancing the anti-tumor effects of ferroptosis inducer FER-1 in ovarian cancer cell lines and mouse xenograft models." (PMID 41421797, 2025). "Besides, in ovarian CSCs, the expressions of CD36 and other enzymes in lipid metabolism such as ACC, stearoyl-CoA desaturase (SCD), and carnitine palmitoyltransferase 1 (CPT1), were upregulated compared to well-established ovarian cancer cells." (PMID 34603046, 2021).
ovarian carcinoma (continued). "Stearoyl-CoA desaturase (SCD1, SCD), an enzyme that catalyses the rate-limiting step in monounsaturated fatty acid (MUFA) synthesis, has been shown to protect ovarian cancer cells from ferroptosis and regarded as a therapeutic target in ovarian cancer." (PMID 33292585, 2020). "CPT1A, SCD and FASN may form an adjustable lipid metabolism enhancing pathway with CPT1A as the center, which plays a key synergistic role in the development of paclitaxel resistance in ovarian cancer." (PMID 38003694, 2023).
hepatocellular carcinoma (65 papers, 2013 to 2025). A malignant tumor that arises from hepatocytes. "RNA-binding protein 3 (RBM3) dynamically adjusts the proliferation of hepatocellular carcinoma cells by regulating the production of SCD-circRNA2 encoded by the 3′-UTR of the stearoyl-CoA desaturase (SCD) gene." (PMID 33928139, 2021). "Specifically, AMPK-mediated downregulation of SCD promotes ferroptosis in hepatocellular carcinoma cells by inhibiting MUFA production." (PMID 37051693, 2023). "Compared to normal hepatocytes, SCD expression levels and the concentration of its MUFA products were increased in aggressive hepatocellular carcinoma and were associated with poor survival times and tumor recurrence." (PMID 37373069, 2023). "Particularly, it has been shown that SCD-circRNA 2, which was derived from the stearoyl-CoA desaturase, was highly expressed in hepatocellular carcinoma tissue and correlated with poor patient prognosis." (PMID 33020462, 2020). "Stearoyl-CoA desaturase 1 (SCD1) is an established molecular target in many primary tumors including breast, lung, pancreatic, colon and hepatocellular carcinomas." (PMID 29552293, 2018). "Reduced LXRα activity has been reported to significantly decrease the expression of SREBP-1c, FAS, ACC and SCD-1 in mice and in hepatoma cells." (PMID 23409094, 2013). "Moreover, the normal upregulation of CES1, which activates the PPAR α-SCD signaling axis, is believed to enhance lipid metabolism and potentially contribute to cisplatin resistance in hepatocellular carcinomas." (PMID 39574476, 2024). "Indeed, in this paper they showed that many cancer cells activate lipid-synthesis pathways to support their rapid proliferation, especially hepatocellular carcinoma implicating two enzymes SCD and FADS2." (PMID 31717414, 2019). "For instance, stearoyl-CoA desaturase 1 (SCD1) utilizes the mechanical signaling pathway to orchestrate lipid metabolism reprogramming and enhance membrane fluidity, thereby facilitating invasive migration and metastasis of hepatocellular carcinoma (HCC) cells." (PMID 40028341, 2025). "Overexpression of RBM3 in hepatocellular carcinoma (HCC) positively correlates to levels of SCD-circRNA 2 generated from the stearoyl-CoA desaturase (SCD) gene." (PMID 34449657, 2021). "Furthermore, RBM3 could promote the growth and proliferation of hepatocellular carcinoma (HCC) cells in the stearoyl-CoA desaturase (SCD)-circRNA-2-dependent manner by control SCD-circRNA-2 formation." (PMID 34804951, 2021). "This alternative metabolic pathway ensures the production of MUFAs when SCD is inhibited, thereby offering the strategy of combined inhibition of both FADS2 and SCD to reduce hepatocellular carcinoma." (PMID 40814339, 2025). "Immunohistochemistry was performed on samples from patients with hepatocellular carcinoma (HCC) to establish the correlation between miR-3180, stearoyl-CoA desaturase-1 (SCD1), and CD36 expression, quantified via qRT-PCR and western blotting." (PMID 37041584, 2023). "In addition, elevated SCD-1 expression was also observed in human prostate cancer, hepatocellular carcinoma (HCC) and clear cell renal cell carcinoma (ccRCC)." (PMID 37151873, 2023). "In hepatocellular carcinoma (HCC), suppression of CES1 leads to a significant reduction in lipid signaling molecules of PPARα/γ, with a notable downregulation of the PPARα/γ target gene SCD, which is associated with tumor metastasis, recurrence, and chemoresistance." (PMID 39472448, 2024). "It has been observed that SCD inhibition upregulates sapienate levels in non-sensitive SCD1 inhibitor tumor cells such as liver carcinoma." (PMID 31936134, 2020). "Second, NR1H3 could bind to SCD in HT29 colorectal adenocarcinoma cells (no similar study was performed with hepatocellular carcinoma cells)." (PMID 35957896, 2022).
hepatocellular carcinoma (continued). "In addition, we have previously reported that a combination of SCD and FADS2 inhibition successfully curbs tumor growth in an orthotopic hepatocellular carcinoma model, albeit not necessarily involving the same mechanism." (PMID 36338708, 2022).
metabolic syndrome (60 papers, 2005 to 2026). A cluster of metabolic risk factors for CARDIOVASCULAR DISEASES and TYPE 2 DIABETES MELLITUS. "SCD is recognized as a pivotal regulator of lipid homeostasis and is implicated in metabolic syndrome development and inflammation." (PMID 41492472, 2026). "Stearoyl-CoA desaturase-1 (SCD1 or delta-9 desaturase, D9D) is a key metabolic protein that modulates cellular inflammation and stress, but overactivity of SCD1 is associated with diseases, including cancer and metabolic syndrome." (PMID 34680068, 2021). "In people, both SCD-1 activity and plasma palmitoleic acid concentration are stimulated by carbohydrate excess and serve as key drivers for de novo lipogenesis and the hyperlipidemia associated with metabolic syndrome." (PMID 38924032, 2024). "In line with this, a significantly decreased hepatic expression of stearoyl CoA desaturase (Scd1), associated with the metabolic syndrome as well as regulation of inflammation, was measured in Calca- and αCGRP-deficient mice while it was overexpressed in liver tissue derived from CTR-deficient mice." (PMID 28666011, 2017). "Other desaturases, including delta-9-desaturase (D9D) or stearoyl-CoA desaturase (SCD), regulate the energy requirement of cells and interact with insulin to influence glucose homeostasis and metabolic syndromes." (PMID 34531722, 2021). "This is in agreement with studies suggesting that deregulation of SCD supports inflammation, atherosclerosis, hypertriglyceridemia, and metabolic syndrome." (PMID 24465667, 2014). "Taken together, all these results highlighted that benzoylpiperidine 89 could be further modified to develop novel and more potent SCD-1 inhibitors useful in the treatment of metabolic syndrome." (PMID 38731421, 2024). "Indeed, other disease states such as insulin resistance, metabolic syndrome, and cancer are also characterized by disturbances in SCD-1 activity." (PMID 20565855, 2010). "The increased expression of stearoyl-CoA desaturase-1 (SCD-1) plays a key role in lipogenic gene expression and in metabolic syndrome, which coincides with marked elevations of lipoprotein lipase (Lpl, 33-fold) and cytosolic acyl-CoA thioesterase-1 (Cte1, 5-fold) in arsenic-induced HCC." (PMID 16507464, 2006). "Indeed, SCD-1 could represent a feasible target for the treatment of metabolic syndrome and other lipid-related diseases." (PMID 38731421, 2024). "Supporting the role of SCD-1 in the development of dyslipidemia and atherosclerosis (at least in an animal model of OSA) is the fact that mice lacking functional SCD-1 have less dyslipidemia and atherosclerosis." (PMID 23346414, 2013).